AGRP (agouti related neuropeptide)
Diseases named in the same sentence as AGRP in open-access papers (continued):
Sharing a sentence is not in itself a finding about the gene and the disease.
Obesity (continued). "Collectively, these findings underscore the important role of RAF1 in AgRP neurons in maintaining energy homeostasis and obesity pathogenesis, positioning it and its downstream pathways as potential therapeutic targets for innovative strategies to combat obesity and related metabolic diseases." (PMID 40432214, 2025). "Furthermore, diet-induced obesity blunts AGRP responsiveness to circulating hormones." (PMID 37443835, 2023). "Considering HFD-fed Syn1-cre; Ghsrf/f mice have more pronounced anti-obesity phenotypes than AgRP-cre; Ghsrf/f mice, the distinctive feeding patterns suggest that eating slowly during the optimal feeding period (dark phase for mice) may be beneficial in combating obesity." (PMID 35204795, 2022). "Furthermore, the excessive expression of AgRP in mice results in obesity." (PMID 33868169, 2021). "Thus, HFD-mediated obesity selectively attenuates lipid-induced inhibition of AgRP neurons and modest weight loss is not sufficient to restore the effects of this macronutrient." (PMID 32720646, 2020). "Interestingly, our finding that AgRP neurons become resistant to both ghrelin and CCK, along with substantial prior evidence of leptin resistance in obesity, suggests that AgRP neurons may become generally resistant to hormonal input following weight gain." (PMID 32720646, 2020). "Moreover, transgenic mice over-expressing AgRP develop early hyperphagia and obesity." (PMID 21544212, 2011). "Since glucocorticoid excess (Cushing’s syndrome) predisposes one to obesity and diabetes both in humans and in animal models, these findings support the hypothesis that reduced HPA axis activity may have contributed to sustained glucose lowering induced by AgRP neuron inactivation." (PMID 40371641, 2025). "To do so, we first examined the expression of Raf1 in AgRP and POMC neurons of diet-induced obesity (DIO) mice." (PMID 40432214, 2025). "These considerations highlight important unanswered questions about interactions between FGF1, AgRP neurons, the HPA axis, and the pathogenesis of obesity and diabetes." (PMID 40371641, 2025). "MC4R blockade induces obesity in rodents, e.g., in mice overexpressing a natural MC4R blocker, an agouti-related peptide (AgRP); MC4R-knockout mice also show an obesity phenotype." (PMID 40232848, 2025). "Obesity results in a relative insensitivity to leptin signaling, and leptin insensitivity in POMC and AgRP neurons leads to obesity and diabetes in patients and animal models." (PMID 40501942, 2025). "Studies have shown that chronic metabolic stress, such as obesity and HFD consumption, leads to chronic hyperactivity of AgRP neurons, which is likely a result of leptin resistance." (PMID 39916981, 2024). "Mechanistic studies revealed that deletion of Rho-kinase 1, a protein kinase involved in cytoskeletal reorganization and neuropeptide release, in both AGRP and POMC neuronal populations resulted in leptin resistance and obesity." (PMID 37443835, 2023). "Taken together, bidirectional manipulations of neurons of the melanocortin pathway (POMC, AgRP, and MC4R neurons) result in severe obesity as predicted while they fail to achieve the expected obesity prevention and reversal phenotypes." (PMID 37069175, 2023). "We have previously shown that the gut-to-brain axis involving taurocholate/FGF15 improved glucose tolerance in multiple models of obesity and diabetes, which was dependent on FGFR1 in AGRP-expressing cells." (PMID 36787185, 2023). "Leptin positively regulates these SNS neurons through MBH-localized AgRP/NPY-, POMC/CART-, and SH2B-expressing neurons since deletion of LepR in those neurons results in obesity with the inefficiency of thermogenesis and lipolysis." (PMID 37547309, 2023). "Collectively, the reducing effects of HMBA on body weight and food intake were completely abrogated by silencing of Myh9 and Actg1 in AgRP and POMC neurons, suggesting that MYH9 and ACTG1 are required for the anti‐obesity effects of HMBA." (PMID 37984341, 2023).
Obesity (continued). "The diet-induced obesity suppressed the neuroendocrine ghrelin system by decreasing ghrelin production in the stomach, as well as by ghrelin resistance in arcuate NPY/AgRP neurons." (PMID 34445772, 2021). "It has been well-documented that leptin exerts an inhibitory effect on food intake and increases energy consumption via suppressing the NPY/AgRP neurons and activating α-MSH/CART neurons in the hypothalamus, thus effectively reversing obesity." (PMID 33868169, 2021). "The disruption of primary cilia in POMC or AgRP neurons through conditional knockout of ciliogenic genes IFT88 and Kif3a promote hyperphagic induced obesity." (PMID 33139642, 2020). "Interestingly, Sirt1 expression was also shown to be affected by aging in the ARC, and it has been suggested that conditional knock-in of Sirt1 in AgRP and POMC neurons could protect against aging-associated obesity by inhibiting feeding and stimulating energy expenditure." (PMID 31309172, 2019). "A DBS neuromodulation approach of the ARC to treat obesity would preferably activate selectively the anorexigenic POMC and/or inactivate the orexigenic AgRP/NPY neurons." (PMID 31057350, 2019). "The relevance of NPY and its role, in combination with other regulatory peptides (POMC, AgRP, MC4-R and SOCS3), was clearly seen in adulthood, when obesity was settled in L-females." (PMID 29329236, 2018). "Constitutive activation of mTORC1 signaling in the AgRP neurons modulates sympathetic tone to increase BAT thermogenesis and energy expenditure and protects against diet-induced obesity." (PMID 30011848, 2018). "Attention has focused particularly on the roles of peripheral α-MSH and AgRP in obesity, and several studies have reported on the peripheral actions of α-MSH and AgRP in the pathophysiology of eating disorders in adults." (PMID 26758700, 2016). "In previous works, under diet-induced obesity (DIO) conditions, orexigenic neuropeptides (AgRP and NPY) were induced while anorexigenic neuropeptides (α-MSH) were reduced by hypothalamic ER stress." (PMID 26901224, 2016). "Genetic ablation of OGT in AgRP neurons inhibits neuronal excitability, promotes WAT browning, and protects mice against diet-induced obesity and insulin resistance." (PMID 26441839, 2015). "The aim of the present study was to assess the genetic variability of AGRP gene and investigate whether the previously reported SNP rs5030980 and the rs11575892, a SNP that so far has not been studied with respect to obesity is associated with increased body mass index (BMI)." (PMID 19602223, 2009). "In addition, activation of non-AgRP, GABAergic neurons in the ARC reportedly drives severe obesity in mice." (PMID 40371641, 2025). "Males born to hyperglycemic dams showed decreased AgRP and α‐MSH projections to the PVN, with an increased number of α‐MSH neurons in the ARC in adulthood, which are accompanied by hyperphagia, hyperglycemia, and obesity." (PMID 40474775, 2025). "Given our current finding that GIPR blockade attenuates glucose-induced AgRP neuron inhibition, we set out to test the hypothesis that HSD-induced obesity would blunt the response of AgRP neurons to DA-GIP." (PMID 40857106, 2025). "Implicit in this observation is that insulin secretion declines in response to AgRP neuron inactivation in these animals — a finding in sharp contrast to the absence of any detectable change of food intake or obesity." (PMID 40371641, 2025). "In NPY-GFP::LIC::Ai9 reporter mice, we observed a subset of AgRP neurons that was LepR negative, suggesting a potential role of this subset in promoting obesity." (PMID 40540394, 2025). "As this effect occurred despite having no detectable impact on food intake, energy expenditure, body weight, or body fat mass, our findings identify AgRP neurons as key drivers of hyperglycemia, but not obesity, in this T2D model." (PMID 40371641, 2025).
Obesity (continued). "Remarkably, early life sensory cues can outweigh the profound effects on AgRP neurons of diet-induced obesity during adulthood, which had no additional detrimental consequences on these neurons." (PMID 41326798, 2025). "AgRP neurons release the neuropeptide AgRP to hypothalamic nuclei such as the paraventricular nucleus (PVN) and dorsomedial hypothalamus (DMH), regulating their functions to reduce EE and promote obesity." (PMID 41037185, 2025). "Additionally, using an HFD-induced mouse obesity model to investigate the effects of SGLT2 inhibitors, we found changes in the expression of AgRP and POMC mRNA depending on the duration of SGLT2 inhibitor treatment." (PMID 39057086, 2024). "Future research should explore the potential mechanisms of diet induced leptin resistance in the absence of obesity (but in the presence of AgRP neuronal hyperexcitability)." (PMID 36725979, 2023). "Although obese patients with mutations in AGRP have not been identified, there is increased expression of AGRP in response to obesity in both mice and humans." (PMID 36472402, 2023). "On the other hand, loss of LepR in POMC/CART, but not AgRP/NPY, neurons in the adult mice promotes obesity only when fed HFD These results suggest that the primary target of leptin is context-dependent." (PMID 37547309, 2023). "Mice lacking SH2B1 display severe obesity, elevated expression of AgRP/NPY, and impaired activation of JAK2 and STAT3." (PMID 38027481, 2023). "Deletion of LepR gene specifically in AgRP/NPY, but not in POMC/CART, neurons in the adult mice (to avoid compensatory effects of gene deletion) causes obesity under a standard chow diet." (PMID 37547309, 2023). "Further, these alterations in gut microbiota have been shown to promote important changes in satiation signals including gut hormones (leptin, ghrelin, GLP-1, peptide YY and CCK) and orexigenic and anorexigenic neuropeptides (AgRP, NPY, POMC, CART) that influence hyperphagia and therefore obesity." (PMID 37571301, 2023). "The increased level of ROS and NO in the first-order neurons into arcuate nucleus, and the aberrant functioning of orexigenic Agouti-related protein (AgRP)/Neuropeptide Y (NPY), anorexigenic pro-opiomelanocortin (POMC)/cocaine- and amphetamine-regulated transcript (CART) can lead to obesity." (PMID 36501129, 2022). "Recent studies have suggested a defective neuron responsiveness in AgRP neurons and CRH neurons by HFD, which may play a critical role in diet-induced obesity." (PMID 33826123, 2022). "Another X-linked gene is O-GlcNAc transferase (OGT), although its functions on body weight balance appears to be site specific, with OGT in orexigenic agouti-related peptide (AgRP) neurons promoting weight gain while OGT in anorexigenic PVH neurons prevent overeating and obesity." (PMID 33826123, 2022). "However, the degree of body weight and fat mass decrease in HFD-fed AgRP-cre; Ghsrf/f mice was much less pronounced than that in HFD-fed Syn1-Cre; Ghsrf/f mice, the later has a remarkable anti-obesity phenotype." (PMID 35204795, 2022). "This may have been due to the increased bodyweight in AgRP‐stimulated mice that could offset the inhibitory effects of AgRP and NPY neuropeptides on GnRH and/or kisspeptin neurons, as prepubertal obesity often advances puberty onset." (PMID 36306199, 2022). "Obesity develops when NPY and AgRP levels rise as a result of prolonged or frequent BPA exposure." (PMID 35328389, 2022). "In those cases, ghrelin resistance was not limited to NPY/AgRP neurons, because ghrelin did not stimulate GH secretion in mice with diet-induced obesity." (PMID 34445772, 2021). "On one hand, the activation of TLR4 signal in AgRP/NPY and POMC neurons decreased the expression of AgRP/NPY and increased the expression of POMC, which induced the reduction of appetite and suggested to be involved in obesity." (PMID 34899611, 2021).
Obesity (continued). "Deletion of Mfn1 or Mfn2 in AgRP/NPY neurons prevents fusion and impairs neuronal firing frequency in diet-induced obesity, illustrating that the induction of mitochondrial fusion is required for the paradoxical neuronal activation of AgRP/NPY neurons following exposure to HFD (Figure 2Cii)." (PMID 33240218, 2020). "As in mammals and birds, MC4R, AgRP, POMC, and MRAP2 have also been identified in some teleost species, and these molecules likely play similar roles in feeding, growth, and obesity within the hypothalamus." (PMID 32987823, 2020). "We also found a possible mechanism of CAP’s anti-obesity effect by enhancing PYY and GLP-1excretion in intestinal epithelial cells, which suppress NPY- and AgRP-expressing neurons and activate POMC- and CART-expressing neurons in the ARC of the hypothalamus, resulting in lower food intake." (PMID 32180694, 2020). "So far, several targets related to the central nervous system (CNS) like 5HT2C, NPY (NeuropeptideY), and AgRP (Agouti-related protein) etc., and the non-central nervous system like pancreatic lipase, leptin, ghrelin etc., were reported as obesity targets." (PMID 31581577, 2019). "This is in agreement with previous reports showing that ghrelin is unable to induce a hyperphagic response in diet-induced obesity and that this effect may be specifically due to ghrelin resistance in NPY/AgRP neurons in the ARC." (PMID 29433631, 2018). "AgRP and NPY are orexigenic factors inducing hyperphagia and obesity." (PMID 30483218, 2018). "Similarly, in AgRP neuron-specific GHS-R knockout mice, diet-induced obesity was mitigated by thermogenesis activation." (PMID 29255175, 2017). "Mice lacking ROCK1 in either POMC or NPY/AgRP neurons, display impaired leptin sensitivity and obesity." (PMID 28270795, 2017). "The diet-induced obesity suppressed the neuroendocrine ghrelin system by decreasing ghrelin production in the stomach, as well as by ghrelin resistance in arcuate neuropeptide Y/Agouti-related peptide (NPY/AgRP) neurons." (PMID 28596789, 2017). "An enduring AgRP-induced blockade of MC4R leads to hyperphagia and obesity." (PMID 27147943, 2016). "It is certain that AgRP neurons are not the only key neurons controlling feeding because lesion of the Arc including AgRP neurons leads to hyperphagia and obesity." (PMID 23346045, 2012). "In our study we showed that hypothalamic progenitor cells express feeding-related neuropeptides and differentiate to mature neurons including those described to be affected by hypothalamic neurodegeneration in obesity and Huntington disease: NPY, AGRP, POMC, CART and Orexin-A neurons." (PMID 21589937, 2011). "Understanding the neurobiological basis by which AgRP neurons regulate consummatory behaviors offers promising avenues for developing treatments for eating disorders and obesity, enabling the targeted modulation of food reward without necessarily altering caloric intake." (PMID 40760098, 2025). "However, HSD-induced obesity did not significantly alter AgRP neuron responses to incretin agonists." (PMID 40857106, 2025). "Although there is not a bona fide asprosin receptor, PTPRD has been identified as a potential orexigenic receptor for asprosin in hypothalamic AgRP neurons, since genetic ablation of PTPRD leads to loss of appetite, resistance to diet-induced obesity, and lack of response to asprosin." (PMID 40871563, 2025). "Thus, we infer that the pronounced hyperinsulinemia characteristic of these animals depends in part on AgRP neuron hyperactivity, and that this effect is not secondary to hyperphagia or obesity." (PMID 40371641, 2025).
Obesity (continued). "Diet-induced obesity does not alter incretin-mediated AgRP neuron inhibition." (PMID 40857106, 2025). "Moreover, leptin treatment does not mitigate the enhanced feeding and obesity in these mice, suggesting that the body weight regulation by ARC GABA neurons and the anti-obesity effects of leptin are not solely dependent on AgRP neurons." (PMID 40130157, 2025). "While our work identifies Raf1 as a novel component in this network, the non-unique phenotype highlights that AgRP neurons may exhibit limited redundancy in maintaining pro-obesity functions." (PMID 40432214, 2025). "Similarly, in the hypothalamus, agouti-related protein (AgRP) expressing neurons displayed enriched OGT, and selective knockout of this enzyme resulted in inhibition of neuronal excitability, protecting mice against insulin resistance and diet-induced obesity." (PMID 39474868, 2024). "Moreover, network construction produced similar results: Rumonococcus, Lachnospiraceae_NK4A136-group, Prevotellaceae_NK3B31_group, and Clostridium_sensu_stricto_1 were involved in the accumulation of IL-1β, TNF-α, MG,AGEs, TG, AgRP, and SOCS3 for the development of obesity." (PMID 38659208, 2024). "In order to verify that KDM4D is necessary to reverse obesity by dieting, we demonstrated that in vivo inhibition of KDM4D activity by pharmacological agent JIB-04 in naïve rats resulted in transcriptional repression of AgRP, decreasing orexigenic signaling, thus inhibiting hunger." (PMID 36817590, 2023). "Another important question not addressed here is whether there is heterogeneity in AgRP neuron responses to diet-induced obesity." (PMID 32720646, 2020). "We hypothesized that maternal HF alters fetal neuroprogenitor cell (NPC) and hypothalamic arcuate nucleus (ARC) development with preferential differentiation of neurons towards orexigenic (NPY/AgRP) versus anorexigenic (POMC) neurons, leading to offspring hyperphagia and obesity." (PMID 33138074, 2020). "Moreover, disruption of GABA release from a specific subset of non-AgRP non-POMC neurons of the arcuate nucleus of mice induced obesity through decreasing energy expenditure." (PMID 30406389, 2019). "For example, central administration of insulin provokes hyperpolarization of ARC-residing AgRP and POMC neurons, whereas neuron-specific ablation of insulin receptors is associated with diet-induced obesity, and ablation from AgRP, but not POMC neurons, alters hepatic glucose production." (PMID 28121620, 2017). "However, circulating levels of MSH and AgRP, and the potential role of these proteins in childhood malnutrition and obesity, have not yet been studied; scant data exist regarding their effects on circulatory function in children." (PMID 26758700, 2016). "Indeed, Lepob/ob mice lacking GluN2B only in AgRP neurons had increased sensitivity towards the anti-obesity actions of recombinant leptin suggesting that GluN2B-NMDARs normally antagonize leptin signaling within hypothalamic AgRP neurons." (PMID 26500840, 2015). "Recent evidence has also demonstrated the importance of AgRP neurons in thermoregulation and specifically, data have shown that inactivation of AgRP neurons promotes retroperitoneal WAT browning and protects mice against diet-induced obesity and insulin resistance." (PMID 26379628, 2015). "Thus, we hypothesize that in these mice, hyperphagia and obesity — but not hyperglycemia — are driven by non-AgRP neurons." (PMID 40371641, 2025). "However, our study reveals that maternal obesity does not affect AgRP circuits during early postnatal life whereas it affects POMC axonal projections, suggesting that distinct mechanisms underlie the effects of maternal HFHS feeding on POMC neurons versus AgRP/NPY neurons." (PMID 32163401, 2020).